MYCN (MYCN proto-oncogene, bHLH transcription factor)
Diseases named in the same sentence as MYCN in open-access papers (continued):
Sharing a sentence is not in itself a finding about the gene and the disease.
tumor (continued). "Interestingly, TAMs can upregulate oncogenic MYC expression in non-MYCN amplified NBL cells, contributing to tumor progression." (PMID 39199637, 2024). "Tivantinib significantly blocks NB cell proliferation and 3D spheroid tumor formation and growth in different MYCN-amplified and MYCN-non-amplified NB cell lines." (PMID 39458991, 2024). "The same study demonstrated that this activator was better at decreasing tumor growth in animals bearing MYCN-amplified tumors than non-amplified tumors." (PMID 39594793, 2024). "Using tumor purity–corrected RNA-seq data from TCGA (Pancan21 dataset, n = 8290 tumors), we found a strong negative relationship between median MYCN expression and median IFN type I signature within cancer types with high MYCN expression." (PMID 38748789, 2024). "The results suggested that MTHFD1 maintained redox homeostasis in MYCN-amplified NB, and inhibiting MTHFD1 in tumor cells may weaken the resistance to oxidative stress, thus preventing the malignant progression of tumors." (PMID 38336749, 2024). "MYCN regulated the expression of SESN1 in NB cells, and knockdown SESN1 increased NB cell proliferation, cell migration, and cell invasion in vitro, and promoted NB tumor growth and shortened tumor‐bearing mice survival time in vivo." (PMID 38516781, 2024). "Given the lower IC50 and Emax values, ceftriaxone had high potency and efficacy, respectively, in MYCN‐amplified tumor cells compared with that in MYCN‐nonamplified tumor cells." (PMID 37975412, 2024). "Studies done in the early 2010s showed that these tumours formed in the retina, lacked RB1 mutations and instead showed amplification of MYCN gene." (PMID 37667345, 2023). "In this study, OGM detected MYCN amplification in three cell lines (NB1691, NBLW and SK-N-BE2(C)), a TERT rearrangement in one cell line (GI-ME-N) and an intragenic ATRX deletion in a NB tumour." (PMID 37958407, 2023). "It is speculated that MYCN and ZBP1 will affect the similarity between KIRC cells and stem cells in different degrees, which means that they will affect the progress of tumor." (PMID 37878133, 2023). "Named based on the expression of previously established marker genes ERBB2 (T062), NTRK1 (T063), MYCN (T064) and TERT (T065), these subtypes may be rooted in the tumor’s lineage." (PMID 36932241, 2023). "It is worth mentioning however, that PIM3 expression is higher in MYCN-amplified versus non-amplified tumours, suggesting possible isoform-specific roles depending on disease stage/genetic characteristics." (PMID 37414143, 2023). "In summary, these findings suggest that the upregulation of Cdkn2a in GTML as compared to GMYC might reflect a clinically relevant feature also present and affecting tumor prognosis between MYC-high and MYCN-high human Group 3/4 MBs." (PMID 36869047, 2023). "In addition, IHC results confirmed that CCNB1IP1 immunostaining was attenuated in the MYCN knockdown group and rescued in the CCNB1IP1 overexpression group in tumour tissues." (PMID 37461251, 2023). "The lack of NB control by survivin inhibition in the transgenic mouse model was not due to the inhibition of survivin in immune cells, as transplantation of NB from Birc5+/- MYCN tg/+ mice into wild-type mice did not decrease tumor growth." (PMID 38136322, 2023). "In our metastatic dataset along with additional primary SCLC patient tumor, circulating tumor cell‐derived xenograft, and patient‐derived xenograft (PDX) datasets, samples overexpressing MYC paralogs (MYC, MYCL, or MYCN) consistently displayed significantly lower CDKN1A expression." (PMID 37491889, 2023). "While our methods detected a MYCN gain for case 48, immunohistochemical staining of the tumor tissue for RB protein showed a lack of nuclear staining." (PMID 37239954, 2023). "Strong oncogenic synergy of MYCN/IGF2BP1 is evidenced in R26IGF2BP1/MYCN mice, showing reduced tumor latency without or mild chromosomal disturbance." (PMID 37246217, 2023).
tumor (continued). "Patients with T cell-inflamed NB tumours displayed enhanced survival compared to their non-T cell-inflamed counterparts, irrespective of MYCN amplification status, suggesting the direct impact of the TME components on patient prognosis." (PMID 37887559, 2023). "The criteria for INRG staging include age, histologic category, grade of tumor differentiation, MYCN status, presence/absence of 11q abnormalities, and tumor cell ploidy." (PMID 40041269, 2023). "In this regard, MET alone was also shown to suppress tumor growth in MYCN-amplified and non-amplified NB-bearing mice." (PMID 37623854, 2023). "In MYCN-amplified NB cells, after inhibiting the expression of PTK2 with two PTK2 small-molecule inhibitors, the proliferation of tumor cells was significantly reduced, the percentage of cells in the G1 phase was significantly increased, and that in the S phase was decreased." (PMID 36770809, 2023). "If Onalespib treatment requires presence of ARF and MYC, rather than MYCN, for successful tumor cell inhibition, it would be expected that D283 and D425 cells would be more sensitive to HSP90 inhibition than DAOY cells." (PMID 36869047, 2023). "Moreover, in a panel of several different tumor types, CNTFR showed low mRNA expression in the majority of the tumors, while in NB (which is known for its connection with MNA and MYCN overexpression) and in SCLC it showed the highest expression." (PMID 36765949, 2023). "Interestingly, SCLC produces the only form of tumor in which all the MYC family genes (MYC, MYCN and MYCL) are found to be altered." (PMID 36765949, 2023). "In support of this notion, we observed either a partial disruption to tumor growth, or no response at all, in MYCN-amplified NB xenografts treated with MET alone or in combination with CP." (PMID 37623854, 2023). "Together, these results suggest that MYCN-driven tumor initiation is accompanied by early and marked upregulation of the MGS, and mitotic dysregulation could be the pathway by which MYCN shifts the premalignant neuroblast toward malignant transformation." (PMID 37958555, 2023). "Furthermore, the tumor either presents a methylation profile aligned with subgroups pHGG RTK1, pHGG RTK2 or pHGG MYCN or it exhibits molecular features as PDGFRA alteration, EGFR alteration or MYCN amplification." (PMID 37561227, 2023). "qRT-PCR analysis of xenograft tumor samples showed that the ADAMTS9-AS2–overexpressing group had higher levels of differentiation markers (Syn and Tau) and lower levels of MYCN and stem cell markers (Nestin and SOX2) compared with SK-N-Be2 cell xenograft vehicle groups." (PMID 37991019, 2023). "Overall confirming that presence of ARF expression, as well as MYC, but not MYCN, are key identifiers of successful tumor cell response and ablation to HSP90 inhibition in both our animal models and in human lines." (PMID 36869047, 2023). "Finally, systemic treatment with BGA002 significantly increased survival in MYCN-amplified SCLC mouse models, including in a multidrug-resistant model in which tumor vascularization was also eliminated." (PMID 36765949, 2023). "Additionally, we have shown that MYCN inhibition by BGA002 has the ability to revert this in the MYCN-related SCLC and NB, leading to potent and specific anti-tumor activity." (PMID 36765949, 2023). "Prognosis in NB is known to be influenced by factors such as age, tumor cell differentiation, and MYCN amplification, but the MYCN gene itself is not easily targeted therapeutically." (PMID 38035110, 2023).
tumor (continued). "In this study, we found that MET decreased cell proliferation and mitochondrial respiration in MYCN-amplified NB cell lines, while the combination of KD, MET, and low-dose CP (triple therapy) also reduced tumor growth and improved survival in vivo in MYCN-amplified NB xenografts." (PMID 37623854, 2023). "Outcomes at two years imply how aggressive the tumor character is, and survival probability at eight years after diagnosis nearly exhibits a plateau even with the MYCN-non-amplified cases." (PMID 36572864, 2022). "Further analysis of patients with available molecular subgroup showed 33 (73.3%) males and 12 (26.7%) females, one patient with residual tumor ≥ 1.5cm2, 39 (86.7%) classic (CMB), 4 large-cell/anaplastic (LCAMB) and 2 desmoplastic (DMB) histology, 2 MYC and 4 MYCN amplified cases." (PMID 35190934, 2022). "Molecular genetic testing showed that the tumor cells lacked IDH gene mutations, LOH of 1p/19q, MYCN amplification, and EGFR alteration." (PMID 35663322, 2022). "Our results demonstrate that HMN-214 significantly inhibits NB spheroid tumor growth in a dose-dependent manner, in contrast to controls in both MYCN-amplified and MYCN-non-amplified spheroid tumors." (PMID 35631350, 2022). "This was not independent of MYCN amplification status, tumor stage or age at diagnosis, which can be explained in part by the regulation of EIF4EBP1 promoter by MYCN which we characterized." (PMID 35379801, 2022). "In the present study, we evaluated whether the binding of MX25-1 to MYCN 3’UTR is able to block its interaction with MDM2 and inhibit both MYCN mRNA and MDM2 expression, resulting in tumor growth inhibition and cell death." (PMID 36505784, 2022). "MYCN has been shown to inhibit the expression of MHC class I antigens that contribute to tumor antigen presentation necessary for immune cells to recognize and attack tumor cells." (PMID 35362827, 2022). "The ITGA9 showed a significant but extremely moderate difference between MYCN-amplified and non-MYCN-amplified tumours." (PMID 36221013, 2022). "Our results demonstrate that the uptake of cystine via xc− is not regulated on tumor progression in adrenergic MYCN-amplified cells." (PMID 35484422, 2022). "Our findings suggest that miR-145-5p can inhibit NED and tumor growth by targeting SOX11, which regulates the expression of MYCN, and that this could be a novel therapeutic strategy for preventing the progression of PCa." (PMID 35368699, 2022). "Our studies show that MYCN protein overexpression, rather than the gene amplification, is critical for determining aggressive tumor behavior." (PMID 35053227, 2022). "Meanwhile, MYCN apparently decreases the interferon signaling, promoting a non-inflamed and T-cell infiltration-poor (“cool”) tumor microenvironment." (PMID 36033519, 2022). "Tumor biopsy is an invasive procedure which sometimes results in inadequate samples and heterogenous MYCN patterns due to an abundance of non-malignant cells." (PMID 35681607, 2022). "This study investigated a high-risk subgroup characterized by the presence of the amplified MYCN oncogene in the tumor regardless of the stage." (PMID 34503173, 2021). "From the perspectives of tumor tissue and cell lines, we simultaneously found that BIRC5 and HK2 may increase tumor malignancy with MYCN amplification, whereas GRID2 and RNASEL were antagonistic to MYCN amplification." (PMID 34746127, 2021). "The tumour microenvironment of MYCN-amplified NBs contains a significantly lower number of immune cells compared to the MYCN-nonamplified counterpart." (PMID 34884690, 2021).
tumor (continued). "Taken together, these data strongly support a transcription-dependent tumor-suppressive role for GLI1 in the more frequent NB cases not harboring MYCN amplifications." (PMID 33921042, 2021). "In particular, telomerase activity was down regulated by 10–15 fold in matched MES cells, but only in MYCN-amplified tumor cell lines, i.e., in LA1-5S and LA1-6S but not in SH-EP1." (PMID 34799676, 2021). "Aiming to reveal the MYCN-dependent miRNome, we evaluate miRNA expression in MYCN-amplified as well as none amplified tumor samples." (PMID 34026620, 2021). "High expression of MYCN in all groups studied suggests a dependency not on the grade of the tumor but even more on its location." (PMID 33430425, 2021). "Moreover, variable degrees of intra-patient tumor diversity were observed, except in P46 epithelial CTCs which harbored recurrent altered regions such as chromosome 2 (ALK and MYCN gains), chromosome 6 (CCND3 gain), and chromosome 17 (SEPT9 gain)." (PMID 34272470, 2021). "In agreement with our hypothesis, we found a low MYCN/MYC mRNA ratio in EPN specimens, where SCs represent a restricted population of the tumor burden." (PMID 33668642, 2021). "The expression of the enzymes was similar in vesicles preparations from patients with MYCN-amplified or non-amplified tumours." (PMID 34847775, 2021). "We separately trained survival prediction models for MYCN amplified and MYCN non-amplified tumors since many genes have a different impact on survival prognosis for these tumor types." (PMID 34556815, 2021). "The dramatic response we observed in both Rosa26_Alkal2;Th-MYCN and Alk-F1178S;Th-MYCN ALK-driven NB GEMMs is interesting in comparison to the results observed in the xenograft setting, where cessation of treatment resulted in tumour regrowth." (PMID 34819497, 2021). "Amplification of the MYCN oncogene has been observed in retinoblastoma, glioblastoma, and medulloblastoma tumors, and raises the possibility that TRIM32 plays a broader role in tumor suppression than previously thought." (PMID 33802079, 2021). "After analyzing any correlations between MYCN and DRD1 expressions and tumor immune-cell types, we found that the high expression of DRD1 in CA was positively correlated with immune activation, and that the high expression of MYCN in CB was positively correlated with immunosuppression." (PMID 34212175, 2021). "We found MYCN protein to be expressed in tumour blastemal cells, and absent in stromal and epithelial components." (PMID 33562123, 2021). "In this review, we have focused on the circuitry linking the oncogenic transcription factors MYCN and PHOX2B with their transcriptional targets ALK and LIN28B and the tumor suppressor microRNAs let-7, miR-34 and miR-204, which should act as down-regulators of their expression." (PMID 34771690, 2021). "One mouse of genotype Rosa26_Alkal2;Th-MYCN was sacrificed after 14 days of treatment (denoted with *), confirming no detectable tumour material on dissection." (PMID 34819497, 2021). "In transgenic fish with overexpression of MYCN and LMO1 oncogenes, fluorescent-positive tumor masses were observed using fluorescent microscopy in the distant regions from the primary tumor site, the interrenal gland region (IRG), as early as five weeks of age." (PMID 33800887, 2021). "Tumours arising in Rosa26_Alkal2;Th‐MYCN were indistinguishable in their presentation from those arising in Th‐MYCN and Alk‐F1178S;Th‐MYCN animals." (PMID 33411331, 2021). "Intratumoral heterogeneous MNA (hetMNA) refers to the coexistence of clustered or scattered single MNA cells and non-MYCN-amplified (non-MNA) tumor cells, a phenomenon that was largely unexplored at the initiation of A-NB94." (PMID 33540616, 2021). "Our analysis of MYCN-amplified NBL cell line and O-PDX models has revealed substantial variations in their promoter activities, which is a potential caveat to the practice of surrogate model (representing primary tumor epigenomes by a few profiled models)." (PMID 33461601, 2021).
tumor (continued). "There is evidence that MYCN promotes a non-inflamed and T-cell infiltration-poor (‘cold’) tumor microenvironment (TME) by suppressing interferon signaling." (PMID 34016720, 2021). "The inhibition of tumor growth was exercised through nearly completed reduction of MYCN protein expression, cell cycle arrest in G2/M phase, but not apoptosis, which is indicative of AURKA inhibition." (PMID 33585252, 2020). "The factors that influence the prognosis include tumor stage, age at diagnosis, histopathology of the tumor, DNA index (ploidy), and the presence or absence of MYCN amplification." (PMID 33053110, 2020). "The NB-hop classifier significantly stratified patients with tumor stage 1, 2, 3, and 4, patients with age < 18 months, patients with age > 18 months, and patients with not amplified MYCN tumor (p < 0.05)." (PMID 32825087, 2020). "Our previous cohort studies in Japan (n = 102) and Europe (n = 50) confirmed an increase in MYCN gene expression in HCC tumor regions as compared to non-tumor regions." (PMID 33937011, 2020). "First, the finding of the MYCN amplification should be considered pathognomonic for a high-grade neoplasm irrespective of the histologic grading." (PMID 32641156, 2020). "As a TF, MYCN regulates many target genes but the critical ones that mediate MYCN tumor initiating functions are not clear." (PMID 33628735, 2020). "It must be mentioned that these tumor cells never reach the MYCN mRNA expression level of MYCN amplified tumors." (PMID 33585251, 2020). "Therefore, due to its multi-targeted effects, inhibiting HSP90 in the MYCN-amplified human IMR-32 cell line would cripple all of its critical, tumor-promoting functions, thereby yielding tangible therapeutic effects on these malignant cells." (PMID 33569349, 2020). "Then we found that immune/stromal/ESTIMATE scores were not correlated with age/chromosome 11q, but tumor stage, MYCN gene amplifications, and chromosome 1p." (PMID 32963529, 2020). "Unfortunately, serial assessment of MYCN amplification of tumor is not possible due to the lack of primary tumor tissue and heterogeneity of tumor in NB." (PMID 32896084, 2020). "Our findings and those of others consistently show that MYCNOS1 transcripts are highly expressed in MYCN-amplified tumor cells compared with non-MYCN-amplified cells." (PMID 33270844, 2020). "Here, a panel of MYCN-amplified/expressing and non-amplified/expressing NB tumour cell lines were screened for reduced viability in the presence of the PARP inhibitors olaparib (AZD-2281) and niraparib (MK-4827)." (PMID 32577161, 2020). "The tumor suppressive properties of DHA and ELOVL2 are repressed by the MYCN and PRC1 jointly, which suggests a new epigenetic mechanism of MYCN-mediated fatty acid regulation and indicates PRC1 inhibition as a potential novel strategy to activate ELOVL2 suppressive functions." (PMID 31856871, 2019). "This implies that MYCN-nonamplified tumours are dependent on the presence of this constitutive active kinase in a higher percentage of the cell population." (PMID 30778092, 2019). "Patients in North America are risk-stratified using a number of features including age at diagnosis, disease stage, tumor histology, MYCN status (amplified versus nonamplified), and tumor cell ploidy." (PMID 30754710, 2019). "In NBLs, the TERT rearrangements were almost mutually exclusive with MYCN and ATRX (associated to another TMM, ALT), stratifying them in two groups of NBLs with very high risk, reinforcing the concept that tumours do not present multiple TMM simultaneously." (PMID 29751586, 2018). "In contrast, DYRK1B and DYRK4 tumor expression was not correlated to MYCN amplification status, and DYRK1A was actually lower in tumors with MYCN amplification." (PMID 29977157, 2018). "While these data match the renowned tumor suppressive function of MRE11, they also highlight that its inhibition might be detrimental in non-MYCN-driven tumors." (PMID 30166519, 2018).